ZMYND8 (zinc finger MYND-type containing 8)
Description:
Chromatin reader that recognizes dual histone modifications such as histone H3.1 dimethylated at 'Lys-36' and histone H4 acetylated at 'Lys-16' (H3.1K36me2-H4K16ac) and histone H3 methylated at 'Lys-4' and histone H4 acetylated at 'Lys-14' (H3K4me1-H3K14ac). May act as a transcriptional corepressor for KDM5D by recognizing the dual histone signature H3K4me1-H3K14ac. May also act as a transcriptional corepressor for KDM5C and EZH2. Recognizes acetylated histone H4 and recruits the NuRD chromatin remodeling complex to damaged chromatin for transcriptional repression and double-strand break repair by homologous recombination. Also activates transcription elongation by RNA polymerase II through recruiting the P-TEFb complex to target promoters. Localizes to H3.1K36me2-H4K16ac marks at all-trans-retinoic acid (ATRA)-responsive genes and positively regulates their expression. Promotes neuronal differentiation by associating with regulatory regions within the MAPT gene, to enhance transcription of a protein-coding MAPT isoform and suppress the non-coding MAPT213 isoform. Suppresses breast cancer, and prostate cancer cell invasion and metastasis.
Synonyms: KIAA1125; PRKCBP1; RACK7; PRO2893
Tractability: PROTAC: UniProt records ubiquitination sites on it; ubiquitination databases record sites on it; its protein half-life has been measured.
Target class: Epigenetic regulator; Bromodomain; Reader
Gene: Protein-coding gene on chromosome 20 (47,209,214 to 47,357,804, reverse strand). Ensembl gene ENSG00000101040.
Subcellular location: Nucleus; Chromosome; Cytoplasm
Subcellular location (Human Protein Atlas): Nucleoli; Nucleoplasm
Pathways (Reactome):
Chromatin organization: Interaction of NuRD complexes with transcription factors
Gene Ontology:
Molecular function: histone H3K14ac reader activity; histone H3K4me1 reader activity; protein binding; protein domain specific binding; transcription corepressor activity; zinc ion binding; DNA-binding transcription factor binding; histone H3 reader activity
Biological process: double-strand break repair via homologous recombination; negative regulation of cell migration; negative regulation of transcription by RNA polymerase II; nervous system development; positive regulation of transcription elongation by RNA polymerase II; protein localization to chromatin; chromatin organization; modulation of excitatory postsynaptic potential; negative regulation of DNA-templated transcription; positive regulation of dendritic spine development; positive regulation of dendritic spine maintenance; positive regulation of filopodium assembly; regulation of DNA-templated transcription; regulation of postsynaptic density protein 95 clustering
Cellular component: chromatin; chromosome; cytoplasm; nucleolus; nucleoplasm; nucleus; site of DNA damage; dendritic shaft; dendritic spine
Genetic constraint (gnomAD): Loss-of-function variants: 37 observed, 144.76 expected, observed/expected ratio (o/e) 0.26, 90% interval 0.2 to 0.34. The upper end of that interval is the gene's LOEUF score, 0.34, which puts it in group 1 of 6, group 1 being the genes least tolerant of losing a copy. Missense variants: 1,065 observed, 1,618.7 expected, observed/expected ratio (o/e) 0.66, 90% interval 0.62 to 0.69. Synonymous variants: 592 observed, 616.43 expected, observed/expected ratio (o/e) 0.96, 90% interval 0.9 to 1.03.
Gene-disease validity (ClinGen):
ClinGen rates the evidence that ZMYND8 causes each of these diseases.
syndromic complex neurodevelopmental disorder (autosomal dominant): Definitive. A disorder that involves more than one phenotype associated with the central nervous system, including but not limited to intellectual disability, autism, and seizures (epilepsy), and also a distinctive pattern of other features including dysmorphisms and/or congenital malformations.
Homologues: Orthologues: chimpanzee ZMYND8 (99% identical), macaque ZMYND8 (98% identical), pig ZMYND8 (93% identical), guinea pig ZMYND8 (92% identical), rat Zmynd8 (91% identical), mouse Zmynd8 (90% identical), dog ZMYND8 (89% identical), rabbit ZMYND8 (88% identical), tropical clawed frog zmynd8 (74% identical), zebrafish zmynd8 (63% identical), zebrafish prkcbp1l (61% identical), Drosophila melanogaster Zmynd8 (28% identical). Paralogues in human: ZMYND11 (16% identical), PHF12 (13% identical), PHF21A (8% identical), PHF21B (6% identical), AIRE (5% identical).
Diseases named in the same sentence as ZMYND8 in open-access papers:
ZMYND8 is named in the same sentence as 49 diseases in open-access papers, as found by Europe PMC text mining. Sharing a sentence is not in itself a finding about the gene and the disease. The quoted sentences say what the papers report.
breast carcinoma (32 papers, 2014 to 2025). "Differences in ZMYND8 expression were observed across various breast cancer subtypes, suggesting its association with subtype-specific biological characteristics." (PMID 41297414, 2025). "Elevated expression of ZMYND8 has been shown to induce an immunosuppressive microenvironment in breast cancer, wherein M2-like tumor-associated macrophages (TAMs) play a critical role." (PMID 41297414, 2025). "Given the association between high ZMYND8 expression and an immunosuppressive microenvironment in breast cancer, we further investigated the function and regulatory mechanisms of ZMYND8 in the TNBC TME using a tumor-bearing model." (PMID 41297414, 2025). "disclosed that ZMYND8 inhibits cytotoxic T cell-mediated anti-tumor immunity by suppressing the release of IFN-β from breast cancer cells, causing breast cancer cells to escape immune surveillance and promote tumorigenesis." (PMID 39742262, 2024). "As a result of alternative splicing, ZMYND8 exon 22 inclusion was linked to a better prognosis in breast cancer patients, enhanced by hnRNPM and opposed by Epithelial Splicing Regulatory Protein 1 (ESRP1)." (PMID 38539439, 2024). "ZMYND8 depletion not only enhances Polycomb-dependent function of EZH2 in hypoxia-exposed breast cancer cells or von Hippel–Lindau (VHL)-deficient ccRCC cells, but also suppresses the FOXM1 transcription program." (PMID 33593912, 2021). "In MDA-MB-231 breast cancer cells, ZMYND8 is directly recruited to metastasis-linked genes SNAI2 and TWIST1, to regulate EMT." (PMID 33670804, 2021). "Copy number increase and overexpression of ZMYND8 were more prevalent in Luminal B subtypes and were significantly associated with shorter survival of breast cancer patients." (PMID 28055972, 2017). "However, in breast cancer samples only four out of 17 genes were significantly and > 1.5‐fold overexpressed, and only one gene—ZMYND8—was associated with patient survival." (PMID 37519063, 2023). "Moreover, ZMYND8 overexpression in doxorubicin-treated cells attenuated the expression of genes (top downregulated) associated with poor prognosis in basal subtype breast cancer patients compared to doxorubicin-downregulated genes." (PMID 33323928, 2020). "In addition, ZMYND8 expression is inversely correlated with metastasis-free survival in breast cancer patients, with high ZMYND8 expression being associated with shorter survival of patients with breast cancer." (PMID 33670804, 2021). "Transwell assay results demonstrated that under both non-Matrigel (migration) and Matrigel-coated (invasion) conditions, ZMYND8-overexpressing breast cancer cells exhibited significantly enhanced migratory and invasive capabilities." (PMID 41297414, 2025). "Data mining of the publicly available BRCA cohort from the TCGA database revealed that ZMYND8 expression was significantly higher in breast cancer tissues than in normal tissues, indicating its potential role in breast cancer pathogenesis." (PMID 41297414, 2025). "Although previous studies have reported the overexpression of ZMYND8 in breast cancer (BRCA), its expression in advanced breast cancer, particularly in TNBC-SM, remains unexplored." (PMID 41297414, 2025). "IHC results also demonstrated that ZMYND8 expression was higher in spinal metastatic lesions than in primary breast cancer tissues." (PMID 41297414, 2025). "On the other hand, the ZMYND8 TF is known to promote breast cancer progression through stem cell modulation conferring therapeutic resistance and protecting it from oxidative stress." (PMID 40723262, 2025). "Recent research explored the role of ZMYND8, a histone reader, in regulating oxidative stress and ferroptosis in breast cancer stem cells (BCSCs)." (PMID 40214466, 2025).
breast carcinoma (continued). "This has been demonstrated for other KDM5 family members, such as KDM5C, which requires its interactions with ERα and ZMYND8 to activate estrogen target genes to promote breast cancer cell growth." (PMID 41308413, 2025). "FBXW7-mediated ubiquitination targets ZMYND8 for proteasomal degradation, whereas a recent study identified USP7 as a deubiquitinase that stabilizes ZMYND8 and thereby promotes breast cancer cell migration and invasion." (PMID 41297414, 2025). "The present study investigates the role of ZMYND8, a hypoxia-responsive epigenetic factor, in regulating carbohydrate metabolism in concert with HIF1α in breast cancer." (PMID 40912652, 2025). "Transwell assays further demonstrated that ZMYND8-OE breast cancer cells promoted the chemotactic migration of macrophages." (PMID 41297414, 2025). "Recent work has identified USP7 as a deubiquitinase for ZMYND8 that promotes breast cancer cell migration and invasion, underscoring the importance of DUBs in modulating ZMYND8-driven oncogenic programs." (PMID 41297414, 2025). "We further showed that deletion of ZMYND8 with MMTV-Cre or K14-Cre significantly increased ROS in tumorspheres prepared from MMTV-PyMT mammary tumors ex vivo." (PMID 38488001, 2024). "For instance, ZMYND8 interacts with HIF-1/2α to enhan elongation of tcehe global HIF-induced oncogenic genes in breast cancer." (PMID 37691108, 2023). "In breast cancer cells, ZMYND8 is expressed as a fusion protein with centrosomal protein 250 (CEP250), a factor required for centriole–centriole cohesion during interphase of cell division." (PMID 36520265, 2022). "In breast cancer and prostate cancers, ZMYND8 has been reported as a tumor suppressor that cooperates with the histone demethylases, KDM5 family functions to remove methyl group from the mark H3K4me3, such as KDM5C." (PMID 36520265, 2022). "ZMYND8, by its dual histone binding ability, induces a terminal differentiation program in breast cancer cells." (PMID 36064715, 2022). "Overexpression of ZMYND8 in doxorubicin-treated cells stimulated those involved in a good prognosis in breast cancer." (PMID 36520265, 2022). "ZMYND8 inhibits migration of breast cancer cells through genomic reading activity of recognizing histone mark." (PMID 36520265, 2022). "It has been shown that, however, upregulation of ZMYND8 by hypoxia-inducible factor (HIF) or ZMYND8 overexpression via positive feedback of the estrogen receptor (ER) pathway was correlated with poor prognosis in patients of breast cancer." (PMID 36520265, 2022). "In breast cancer cells, ZMYND8 interacts with HIF1A and HIF2A by binding to the HREs H3K14ac and H4K16ac; subsequently, the ZMYND8/HIF axis increases breast tumor angiogenesis and decreases cancer cell death to promote metastasis." (PMID 35659268, 2022). "Data from mouse mammary tumor and human breast cancer models show that the ZMYND8 acting as histone reader was selectively expressed in breast cancer stem cells (BCSCs) and promotes epithelial-mesenchymal transition (EMT)." (PMID 36520265, 2022). "Transcriptionally, ZMYND8 can target oncogenes, multi-drug resistance genes, and stemness genes in breast cancer that are maintained in a poised epigenetic state and can repress them in association with KDM5C and EZH2." (PMID 36064715, 2022). "In MDA-MB-231 breast cancer cells, ZMYND8 upregulates differentiation genes and induces cellular differentiation." (PMID 33670804, 2021). "When exposed to hypoxic condition, with 1% O2 for 12 days, the MDA-MB-231 breast cancer cells with ZMYND8-knockout showed decreased colony formation, migration, and invasion, compared to parental cells." (PMID 33670804, 2021). "Similar to the findings in breast cancer cells, the co-IP assay demonstrated that ZMYND8 and FOXM1 interacted with each other at the endogenous level in ccRCC cells." (PMID 33593912, 2021).
breast carcinoma (continued). "In contrast, invasive MCF-7 or 4T1 breast cancer cells overexpressing ZMYND8 show a reduction in the tumor size and tumor weight in mice, compared with the control." (PMID 33670804, 2021). "In MDA-MB-231 breast cancer cells, ZMYND8 is recruited to its target genes by binding to H3K36me2 and H4K16Ac." (PMID 33670804, 2021). "In a three-dimension-based assay, ZMYND8-null ZR-75-30 breast cancer cells show increased anchorage-independent growth, migration, and invasion, which can be reversed by restoration of ZMYND8." (PMID 33670804, 2021). "We found that MMP genes, known targets of the EZH2-FOXM1 complex, were down-regulated after ZMYND8 KO in hypoxia-exposed breast cancer cells." (PMID 33593912, 2021). "In breast cancer, ZMYND8 was found to interact with HIF-1α and HIF-2α, and it can also recruit of BRD4 and release paused RNA polymerase II to enhance the HIF-induced oncogenicity." (PMID 34834420, 2021). "In HeLa and MCF7 breast cancer cells, knocking down ZMYND8 increases the proliferation by about two folds, whereas ZMYND8 overexpression reduces it by about 2.5 to 3 folds." (PMID 33670804, 2021). "In ZR-75-30 breast cancer cells, ZMYND8 promotes the recruitment of KDM5C to the super-enhancer region, shown by the co-binding of ZMYND8 and KDM5C to 88.7% super-enhancers." (PMID 33670804, 2021). "Knocking out ZMYND8 can enhance the tumor growth in a mammary fat pad xenograft model of ZR-75-30 breast cancer cells." (PMID 33670804, 2021). "An in vivo study also showed that ZMYND8 overexpression significantly reduces the subcutaneous 4T1 murine breast cancer growth and increases the expression of differentiation-related genes, including CK5, CK18, CK19, and EPCAM in Balb/c mice." (PMID 33670804, 2021). "The induction of breast cancer cell differentiation by ZMYND8 was noted through the H3K36me2/H4K16ac reader function of ZMYND8." (PMID 33670804, 2021). "We further confirmed that ZMYND8 KO increased the overall level of H3K27me3 in MDA-MB-231 breast cancer cells, and that this only occurred in cells under hypoxia." (PMID 33593912, 2021). "Increased metastatic ability of MDA-MB-231 LM2 breast cancer cells, induced by ZMYND8 knockdown, can be partially reversed by simultaneous knockdown of TROJAN." (PMID 33670804, 2021). "On the contrary, ZMYND8 and doxorubicin upregulated genes had minimal effect on prognosis in breast cancer patients compared to doxorubicin-upregulated genes." (PMID 33323928, 2020). "Previously, we have shown that in luminal breast cancer cells, ZMYND8 regulates the migratory potential and suppresses EMT through its chromatin reader function." (PMID 33323928, 2020). "Collectively, our work identifies ZMYND8 as an epigenetic therapeutic tool that can be used in combination with chemotherapy for combating breast cancer." (PMID 33323928, 2020). "We also observed that ZMYND8 expression was low in the basal subtype of breast cancer cells (MDA-MB-231 and MDA-MB-468) when compared to MCF-7 cells." (PMID 33323928, 2020). "In the present study, we demonstrate a novel anti-chemo-resistance role of ZMYND8, where through its repressive function it re-sensitizes breast cancer cells to chemotherapy." (PMID 33323928, 2020). "In the present study, we delineate the role of ZMYND8 as a potent repressor of chemo-resistance in breast cancer cells." (PMID 33323928, 2020). "Collectively, our findings indicate that poised chromatin is instrumental for the acquisition of chemo-resistance by cancer cells and propose ZMYND8 as a suitable epigenetic tool that can re-sensitize the chemo-refractory breast carcinoma." (PMID 33323928, 2020). "Previous studies have shown that ZMYND8 levels are significantly lower in aggressive breast cancers, such as basal subtype tumors and higher levels in luminal breast cancers." (PMID 33323928, 2020).